ROBO3 (roundabout guidance receptor 3)
Diseases named in the same sentence as ROBO3 in open-access papers (continued):
Sharing a sentence is not in itself a finding about the gene and the disease.
tumor (9 papers, 2016 to 2024). "We observed that ROBO3 promoted tumor progression, and therefore, genetic inactivation of ROBO3 was associated with reduced ascites, reduced metastasis, and a substantial increase in survival." (PMID 35993361, 2022). "The six-BMRGs risk score, comprising CD151, CTSA, MMP1, ROBO3, ADAMTS5 and MEP1A, was established for the prediction of clinical prognosis, tumor microenvironment characteristics, and immunotherapy response in HCC." (PMID 39070142, 2024). "We therefore focused on Y705 phosphorylation (hereafter referred to as p-STAT3) and its role in ROBO3-mediated tumor progression." (PMID 35993361, 2022). "Together, these findings identify the induction of actin-mediated cell protrusions and inhibition of apoptosis as two mechanisms through which ROBO3 contributes to tumor aggressiveness." (PMID 36057630, 2022). "Collectively, we identified a new short isoform of the murine Robo3 gene giving rise to an approximatively 28 kDa protein and that likely plays a role in increased tumor cell aggressiveness upon chemotherapy." (PMID 36057630, 2022). "Here, we examined the role of axon guidance signaling in subtype specificity and focused on ROBO3, which has previously been attributed to a particularly aggressive tumor behavior and poor clinical outcome in patients with PDAC." (PMID 35993361, 2022). "IL-6–induced activation of the ROBO3/STAT3 pathway in CLA-like tumor cells resulted in the induction of BL-characteristic gene signatures and the acquisition of an EMT-like phenotype." (PMID 35993361, 2022). "In these patients, longer overall survival was observed in patients with high tumor expression of Robo2 compared with patients with low Robo2 expression, whereas the opposite pattern was observed for Robo3 expression." (PMID 32670371, 2020). "To evaluate whether ROBO3 signaling maintained BL tumor progression, we orthotopically implanted dCas9-ROBO3 and LacZ control BL (PANC1) cells into the pancreas of immunodeficient mice." (PMID 35993361, 2022). "In the mouse model, the high expression of Robo3 promoted both tumor growth and liver metastasis." (PMID 32670371, 2020). "Moreover, its expression increased in parallel with the tumor stage, and Robo3 levels correlated negatively with those of Robo1 and Robo2." (PMID 32670371, 2020). "To investigate this further, we performed Phalloidin stainings of actin fibers in HCC1806 cells after ROBO3 knockdown and observed a significant reduction of actin-mediated cell protrusions, offering a possible mechanistic insight into the previously observed tumor cell migration impairments." (PMID 36057630, 2022). "mRNA levels of SLIT2, ROBO2, ROBO3, ROBO4 were significantly downregulated in tumor tissues compared to normal tissues." (PMID 35053460, 2022). "Furthermore, to evaluate the role of neoantigen-specific CD8+ T cells in tumor immunity, they implanted WHIM30 tumor sections into immune-compromised mice and adoptively transferred autologous PBMCs stimulated with PALB2, ROBO3, or CMV peptides." (PMID 38920970, 2024). "However, the functional significance of ROBO3 in PDAC plasticity and tumor progression are poorly understood." (PMID 35993361, 2022). "siRNA-mediated silencing of ROBO3 did not affect tumor cell viability (data not shown), but tumor cell invasiveness was significantly reduced in PDX-derived primary PDAC cell lines." (PMID 35993361, 2022). "Consistent with the view that the ROBO3/AXL regulatory network promoted tumor aggressiveness through the IL-6/STAT3 axis, we observed significantly reduced expression of AXL and p-STAT3 in dCas9-ROBO3 tumors, whereas tumors derived from LacZ showed robust expression of AXL and p-STAT3." (PMID 35993361, 2022). "Interestingly, gene sets enriched for inflammatory responses, ECM organization, and fibroblast migration were negatively enriched in ROBO3- and AXL-depleted tumor cells." (PMID 35993361, 2022).
tumor (continued). "Moreover, the relevance of ROBO3-dependent STAT3 activation in BL subtype identity and plasticity was supported by decreased expression of the p-STAT3 downstream target WNT10A, a member of the canonical WNT pathway and driver of EMT-related tumor cell invasion." (PMID 35993361, 2022).
cancer (8 papers, 2016 to 2025). A tumor composed of atypical neoplastic, often pleomorphic cells that invade other tissues. "The result of the in silico analysis indicates different TFs, whose participation in cancer-associated pathways are already known and could also play a role in the regulation of Robo3 isoform expression." (PMID 27660555, 2016). "Despite various studies on ROBO3 expression in neuronal systems and cancer and reports on several slightly divergent gene variants, this greatly shortened isoform of ROBO3 has, to our knowledge, never been described and uncovers a clear gap in our understanding of ROBO3 function." (PMID 36057630, 2022). "For the first time to our knowledge, we provide experimental evidence for the existence of a ROBO3/AXL/p-STAT3 regulatory axis in cancer." (PMID 35993361, 2022). "The upregulation of Robo3 particularly drew our attention because of its dramatic and consistent upregulation across experimental systems, and its potential implication in cancer cell proliferation and metastasis." (PMID 36057630, 2022). "In contrast, Nakamura and colleagues recently reported a reduction of ROBO3 levels in invasive malignancies of the breast when compared with normal tissues and postulated a negative regulation of metastatic behaviors by Neural EGFL Like 2 (NELL2)/ROBO3-signaling." (PMID 36057630, 2022). "Studies assessing the function of ROBO3 in cancer are very scarce." (PMID 36057630, 2022). "This anonymity may explain why ROBO3 has been largely overlooked in studies of ROBO/SLIT signaling in cancer, and its discovery, therefore, opens the field to future investigations." (PMID 36057630, 2022). "It was evident that ROBO3 mediated PDAC aggressiveness in vitro as well as in vivo; however, pharmacological agents that could target ROBO3 in any cancer type have not been reported to our knowledge." (PMID 35993361, 2022).
ROBO3 also shares sentences with these, for which no sentence is quoted: fibrosis of the (2 papers); amyotrophic lateral sclerosis (1); autism (1); cardiomyopathy (1); congenital cataracts (1); Duane retraction syndrome (1); embryonic carcinoma (1); Ewing sarcoma (1); familial hypercholesterolemia (1); limb-girdle muscular dystrophy (1); multiple sclerosis (1); neurodevelopmental disorder (1); neurological disease (1); non-small cell lung carcinoma (1); Obesity (1); oral squamous cell carcinoma (1); sarcopenia (1); schizophrenia (1); visual disorders (1).